RNU6-1338P (RNA, U6 small nuclear 1338, pseudogene)
Gene: Small nuclear RNA gene on chromosome 6 (75,593,055 to 75,593,145, forward strand). Ensembl gene ENSG00000252137.
Homologues: Orthologues: macaque U6 (95% identical), guinea pig U6 (75% identical), dog U6 (69% identical), dog U6 (66% identical). Paralogues in human: RNU6-298P (84% identical), RNU6-429P (80% identical), RNU6-106P (78% identical), RNU6-1304P (78% identical), RNU6-16P (78% identical), RNU6-770P (78% identical), RNU6-1209P (77% identical), RNU6-1255P (77% identical), RNU6-1316P (77% identical), RNU6-181P (77% identical), RNU6-393P (77% identical), RNU6-797P (77% identical), and 1286 more.